MIR6801 (microRNA 6801)
Synonyms: hsa-mir-6801
Gene: MicroRNA gene on chromosome 19 (52,222,020 to 52,222,098, forward strand). Ensembl gene ENSG00000274380.
Homologues: Orthologues: chimpanzee MIR6801 (100% identical).